BAX (BCL2 associated X, apoptosis regulator)
Diseases named in the same sentence as BAX in open-access papers (continued):
Sharing a sentence is not in itself a finding about the gene and the disease.
breast cancer (continued). "However, CD44 overexpression only slightly mitigated the levels of proapoptotic proteins BID and BAX, which were increased in MARCH8-GFP-overexpressing cells, suggesting that additional targets of MARCH8 are responsible for the alteration of proapoptotic signals in breast cancer cells." (PMID 34067416, 2021). "Although the role of BCL-2, BAX, and HER2/neu is established in breast cancer pathogenesis, the exact molecular mechanism is still not clear." (PMID 33708254, 2021). "Furthermore, reduction in BAX/BAK ablated the negative impact of both genetic and pharmaceutical targeting of MCL-1 in breast cancer stem cells." (PMID 33785871, 2021). "In the absence of BAK and BAX, genetic deletion of MCL1 has no impact on breast cancer cells." (PMID 34475520, 2021). "However, paclitaxel sensitivity was not affected in bax−/− MEFs or in human breast cancer cells in which BAX was down-regulated, suggesting that paclitaxel-induced apoptosis is BAK-dependent, but BAX-independent." (PMID 23577147, 2013). "First, in breast cancer, there was no induction of apoptosis through the intrinsic pathway because the mitochondrial membrane potential was not reduced in human epidermal growth factor receptor 2(HER-2)-expressing breast cancer BT-474 cells without the effect of Bcl-2 or BAX." (PMID 36142874, 2022).
colon carcinoma (90 papers, 2007 to 2025). "Capsaicin has an anticancer impact on HCT116 and LoVo cells (human colon cancer cells) through influencing cell cycle G0/G1 phase arrest and apoptosis, which was associated with an elevate of p21, BAX, and cleaved PARP." (PMID 35990343, 2022). "Frameshift mutations were seen present in both BAX alleles in some MMP+ colon tumour cell lines and in primary tumours." (PMID 35057823, 2022). "BCL-2-associated X (BAX) is an apoptosis regulator that can be spliced into a unique Bax isoform (Bax∆2) in colon cancer cells because of BAX microsatellite G7/G7 alleles." (PMID 34330892, 2021). "The molecular docking analysis data of selected colon cancer linked proteins such as BAX, COX-2 Cas 3 and Cas 9 with piperine is reported for further consideration." (PMID 32884209, 2020). "Additional genetic variants retaining significance by PACT were rs6983267 in C-MYC previously identified in a meta-GWAS, rs235770 in BMP2 previously associated with colon cancer risk, and a novel association of rs4645887 in BAX." (PMID 31027226, 2019). "For example, the colon cancer HC49T had G7/G7 homozygous mutation of BAX in the spheroid-derived DNA." (PMID 30680068, 2018). "Owing to the direct interaction of AMPK by thalidezine, we determined the role of AMPK in thalidezine-mediated autophagic cell death in DLD-1 BAX-BAK DKO apoptosis-deficient colon cancer cells." (PMID 28404910, 2017). "TR109 (stage IVA, adenocarcinoma, 59-year-old male with meningeoma angiomatosum gradus 1) has a BAX frame-shift mutation c.121dup characterized as pathogenic and with high impact on protein function and reported in carcinoma of colon, and inborn genetic diseases." (PMID 38893104, 2024). "Moreover, decline of BAX/BCL-2 ratio results in resistance to apoptosis[32 ▶], and reduced expression ratio of BAX/BCL-2 genes in colon cancer causes apoptosis resistance[32 ▶]." (PMID 32429645, 2020). "Expression data from the oncoDB database indicate that the expression of BAX is up-regulated in colon cancer (n = 308) compared to normal tissues (n = 41), whereas the expression of Bcl-2 is down-regulated." (PMID 41180483, 2025). "Another study on colon cancer cell line (LS-180) showed that treatment with 100 and 150 μM concentrations of astaxanthin increased BAX gene expression compared to the control group, though this increase was not statistically significant (P > 0.05)." (PMID 39918669, 2025). "An isogenic model of BAX knockout in human colon carcinoma cell line HCT116 in vitro and in tumor xenografts in vivo." (PMID 38203812, 2024). "Pyroptosis in colon cancer cell lines can be mediated by BAK1 or BAX alone, and caspase 3 activity is required in BAK/BAX-mediated pyroptosis." (PMID 37337018, 2023). "Research has also demonstrated that QR promoted the expression of caspase-3 and increased the BAX/BCL-2 ratio to induce apoptosis in human HT-29 colon cancer cells." (PMID 35479514, 2022). "The findings of this study revealed that pterostilbene significantly enhanced the transcriptional activity of the BAX gene in HT-29 colon cancer cells at all concentrations used." (PMID 35056682, 2022). "In this study, we also demonstrated the competitive relation between GAS5 and miR-128-3p on BAX regulation and its contribution as a ceRNA in anti-cancer drug resistance of colon cancer cells." (PMID 36672566, 2022).
colon carcinoma (continued). "We demonstrate that lncRNA GAS5 enhances BAX expression by interfering with miR-128-3p, thereby contributing to decreasing resistance of colon cancer cells in response to anti-cancer drugs." (PMID 36672566, 2022). "We have been able to confirm in colon cancer cells that increased DLG2 results in an increase in BAX and a decrease in BCL2 resulting in lower cell proliferation." (PMID 35499706, 2022). "β-sitosterol reduced the expression of both Bcl-2 and “cellular inhibitor of apoptosis protein-1” (cIAP1), while inducing the activation of BAX and cytochrome C in the human colon cancer cells HT116." (PMID 34679718, 2021). "Colon cancer cells treated with carnosol had reduced viability, increased apoptosis, increased pro-apoptotic BAX expression and decreased anti-apoptotic Bcl-2 expression." (PMID 33049974, 2020). "Previous experiments have reported a significant rise in the BAX/BCl2 ratio following the administration of myricetin in human hepatocarcinoma and human colon cancer." (PMID 33369440, 2020). "Our data suggested that DLD-1 colon cancer cells with BAX/BAK double-knockout were selectively resistant to a panel of FDA-approved drugs (27 out of 66), including etoposide." (PMID 31551763, 2019). "In this study, we investigated the mechanism underpinning the chemoresistance of DLD-1 BAX–BAK DKO colon cancer cells." (PMID 31551763, 2019). "Taken together, BAX and BAK deficiency in the DLD-1 colon cancer cells downregulated the expression of XPC and altered the energy metabolism of cancer cells via the upregulation of glycolysis implicating the development of drug resistance." (PMID 31551763, 2019). "For clarifying the association of BAX and BAK with the development of drug-resistant phenotype of colon cancers, isogenic DLD-1 WT cancer cells and DLD-1 BAX–BAK DKO cancer cells were used as the cellular model in this study." (PMID 31551763, 2019). "In this study, the effect of deficiency of both BAX and BAK on the transcription profiling in DLD-1 colon cancer cells was examined." (PMID 31551763, 2019). "In the current study, we found that the administration of Epo with LFM-A13 resulted in increased apoptosis in both colon cancer lines, as evidenced by the clear increase in the BAX/BCL-2 ratio." (PMID 29690619, 2018). "The artemisinin family promotes apoptosis via a caspase-dependent pathway in leukemia, or an independent pathway activating BCL2-associated X protein (BAX), a pro-apoptotic molecule, in human colon cancer cells." (PMID 28737711, 2017). "Concomitantly, the amount of energy production in the form of ATP was significantly suppressed in HeLa cells and DLD1 BAX-BAK DKO apoptosis-resistant colon cancer in response to thalidezine treatment." (PMID 28404910, 2017). "This was investigated in the present study using an isogenic pair of HCT116 human colon carcinoma cell lines that differed only in the expression of BAX." (PMID 24185264, 2013). "In conclusion, we demonstrate that BAX is a critical requirement for the induction of apoptosis in a human colon carcinoma model in response to 17-AAG." (PMID 24185264, 2013). "Using an isogenic model for BAX knockout in HCT116 human colon carcinoma cells, we demonstrate the induction of BAX-dependent apoptosis at pharmacologically relevant concentrations of the HSP90 inhibitor 17-AAG both in vitro and in tumor xenografts in vivo." (PMID 24185264, 2013).
colon carcinoma (continued). "We recently reported the potential for increasing the therapeutic effectiveness of HSP90 inhibitors by decreasing survival signaling and enhancing the apoptotic response in BAX+/− HCT116 colon tumor xenografts by co-administration of TRAIL." (PMID 24185264, 2013). "Following five daily i.p doses of 80mg/kg 17-AAG to athymic mice bearing isogenic HCT116 BAX+/− or HCT116 BAX−/− human colon cancer xenografts, a clear effect on the growth of both tumor models was observed." (PMID 24185264, 2013). "To test this we used an isogenic pair of HCT116 colon cancer cells, in one member of which BAX was knocked out using homologous recombination." (PMID 24185264, 2013). "For example, administration of crude extract of garlic to a human colon cancer cell line induced apoptosis by increasing the levels of BAX, CYCS (previously known as cytochrome c) and CASP3 activity while it decreased the mitochondrial membrane potential." (PMID 19552815, 2009). "Our data nicely confirm recent preclinical data showing that BAX is of crucial significance for the induction of apoptosis by 5-FU in colon cancer cell lines." (PMID 17426704, 2007). "The increase in BAX/BCL-2and active caspase-3/pro-caspase-3 ratios indicated that Sch B mightinduce human colon cancer cell death by promoting apoptosis." (PMID 38481680, 2024). "In our study, ADAP1‐NOC4L overexpression increased cell motility and invasiveness, which was in the same way as MMP9, BCL2 expression, and BAX downregulation and thus could be inferred to be effective in colon carcinoma cell metastasis." (PMID 35702822, 2023). "In colon cancer, metformin monotherapy was more effective than active vitamin D3 (VD3) against cancer, resulting in higher levels of p21, p27, phosphatase and tensin homolog (PTEN), BCL2-associated X protein (BAX), cytochrome C (Cyto-C),and caspase-3(Casp-3)." (PMID 35610639, 2022). "A similar differential modulation of the BAX and Bcl-XL ratio by two-drug combinations was demonstrated in studies using human colon tumor cells in the past, which was implicated in the development of cancer and related to the mechanism of cell death induced by pro-apoptotic agents." (PMID 36515436, 2022). "In addition, BAX changes the anti-apoptotic effect of BCL-2 protein resulting in release of cystolic mitochondrial cytochrome c of colon cancer human cells." (PMID 34069111, 2021). "Similar results were obtained with BAX/BAK DKO human colon cancer HCT116 cells, which are more resistant than WT cells in response to mitoxantrone, cisplatin, and oxaliplatin, similarly susceptible to CytD and only partially resistant to Noco, paclitaxel, docetaxel, and vinblastine." (PMID 34725331, 2021). "We confirmed that Septin4 can promote the apoptosis of colon cancer cells by binding to BAX." (PMID 32398959, 2020). "The results showed that Septin4 promoted apoptosis of colon cancer cells by binding to BAX." (PMID 32398959, 2020). "Therefore, we reported here a new molecular pathway of BAX/BAK-induced drug resistance of DLD-1 colon cancer cells which is mediated by the downregulated expression of the XPC gene via the further heightening of glycolytic process." (PMID 31551763, 2019).
colon carcinoma (continued). "In this study, isogenic DLD-1 colon cancer cells and the BAX and BAK double knockout counterpart were used as the cellular model to investigate the role of BAX/BAK-associated signaling network and the corresponding downstream effects in the development of drug resistance." (PMID 31551763, 2019). "In addition, expression of the pro-apoptotic protein, BAX, was also induced by treatment with Mimic-1 in colon cancer cells while the expression of BCL2 was suppressed." (PMID 29507661, 2018). "Mononucleotide tracts in the coding regions of the TGFBR2 and BAX genes are commonly mutated in microsatellite instability-high (MSI-high) colon cancers." (PMID 21949851, 2011). "For this reason, we examined, in a well-characterised, homogeneous collective of patients, whether BAX has a prognostic influence in stage III colon carcinoma treated by adjuvant chemotherapy." (PMID 17426704, 2007). "Thus, preclinical data showing BAX expression to be of vital impact for 5-FU-induced apoptosis in colon cancer cell lines are supported by the data presented here." (PMID 17426704, 2007). "In addition, Septin4 and BAX interact to regulate the apoptosis of colon cancer cells." (PMID 32398959, 2020). "It has been concluded that the BCL2/BAX expression ratio may be considered as prognostic factor in low grade urinary bladder cancer, and also loss of BCL2 expression can be a prognostic factor in recurrent colon cancer." (PMID 28948511, 2017). "In colon tumors, immunohistochemical analysis demonstrated that regions of tumor that stained positive for pimonidazole, a hypoxia probe, displayed decreased levels of the proapoptotic Bcl family members, BH3-interacting domain death agonist (BID) and Bcl2-associated X (BAX)." (PMID 28383481, 2017). "The discovery that BAX-incompetent, unprimed TIS phenotypes in LoVo colon cancer cells retain sensitivity to the BCL-xL-specific BH3 mimetic A1331852 extends our current paradigm of senescence-associated vulnerabilities based on BH3 profiling." (PMID 40055336, 2025). "It was found that the geranyl acetate at high concentrations exhibit anticancer activity against colon cancer via the downregulation of anti-apoptotic BCL-2 protein and upregulation of apoptotic BAX protein in the colon cancer cells." (PMID 39298035, 2024). "Recent studies have shown that the BAK/BAX and caspase-3/GSDME axis mediates chemotherapy-induced pyroptosis in colon cancer cells." (PMID 38104141, 2023). "In a similar study, when apigenin was used in combination with the BCL2 inhibitor navitoclax for 48 h, there was an upregulation of BAX and BIM gene expression and protein levels, which led to apoptotic cell death in colon cancer (HTC-116) cells." (PMID 35614109, 2022). "Allicin can induce apoptosis in the colon cancer HCT116 cell line via the mitochondrial-dependent pathway, as it results in an increase in CYCS and apoptosis regulator BAX protein level but a reduction in the expression of the anti-apoptotic protein BCL2." (PMID 36497321, 2022). "The response of XPC knockdown was comparable to those observed in DLD-1 BAX–BAK DKO cells (IC50 value > 40 μmol; RF = 13.22) suggesting the enhancing role of XPC in the development of resistance in DLD-1 colon cancer cells model against chemotherapy." (PMID 31551763, 2019).